SIX1 (SIX homeobox 1)
Diseases named in the same sentence as SIX1 in open-access papers (continued):
Sharing a sentence is not in itself a finding about the gene and the disease.
tumor (continued). "Our study also showed that EYA1 is responsible for SIX1-induced STAT3 signaling activation, indicating disruption of EYA1 function may suppress the SIX1-mediate tumor growth in PTC." (PMID 31921695, 2019). "Our results open the possibility that SIX1 might play a role in coordinating both processes in tumor cells, and future work should address this interesting question." (PMID 30723235, 2019). "Of note, tumors with SIX1 overexpression showed a faster growth rate and reached larger size and weight at the end of the experiment, indicating that SIX1 promotes tumor growth in this context." (PMID 30723235, 2019). "In addition, SIX1 overexpression promotes tumour lymphangiogenesis by coordinating TGF‐β signals that increase expression of VEGF‐C." (PMID 29435409, 2018). "Moreover, our data show that stable inhibition of Six1 decreases tumour growth in a xenograft model." (PMID 28388884, 2017). "Conclusively, we hypothesized that decreased expression of Six1 would also result in a reduced number of tumour cells with a CSC-phenotype." (PMID 28388884, 2017). "SIX1 could modulate cell cycle and proliferation of tumor cells by transcriptionally regulating the expression of numerous genes." (PMID 28573504, 2017). "After that, we confirmed that miR-30a could directly target SIX1, a novel tumor suppressor gene, in PCa cells." (PMID 28573504, 2017). "Interestingly, in the tumour specimens of the Panc1shctrl group, we observed an increased expression of Six1 at the invasive edge where EMT plays an important role for tumour invasion." (PMID 28388884, 2017). "The upregulation of SIX-1 in primary tumor may increase peritumoral lymphatic density, promote lymphangiogenesis and LN metastasis in cervical cancers by increasing the expression of VEGF-C." (PMID 28036019, 2016). "SIX1 transcriptionally activates VEGF-C, and overexpression of SIX1 in tumor cells may abrogate the inhibitory effect of TGF-β on lymphangiogenesis by upregulating VEGF-C." (PMID 27203207, 2016). "The homeotic transcription factor Six1, which is involved in breast cancer progression and metastasis through upregulation of miR-106b∼25, switches the TGFβ signaling from being tumor suppressive to tumor promotional." (PMID 26405162, 2015). "SIX1 promotes mesenchymal-to-epithelial transition in different tumor types." (PMID 26317783, 2015). "Overexpression of Six1 mRNA was significantly correlated with tumor stage (P = 0.018)." (PMID 23527134, 2013). "Interestingly, EMT has recently been associated with stem cell characteristics, and indeed we found that Six1 overexpression in mammary epithelial cells led not only to tumor formation, but also to an expansion of mammary stem/progenitor cells." (PMID 20074369, 2010). "Although overexpression of Six1 mRNA in tumour tissues of HCC patients was significantly correlated with their positive Six1 protein expression, the percentage of Six1 protein overexpression in tumour tissues was lower than the percentage of Six1 mRNA overexpression." (PMID 17008870, 2006). "Although Six1 protein had not significant association with tumour size (P=0.268), more than 60% (48 of 77) of HCC patients with tumours larger than 5 cm showing positive Six1 protein expression, indicating its probable function on tumour progression." (PMID 17008870, 2006). "All tumour tissues with positive Six1 protein expression could match with their positive mRNA expression except one case." (PMID 17008870, 2006). "Additionally, we calculated the Pearson correlation between SIX1 expression and ploidy in each tumor and observed a significant positive correlation in 5 tumors, including BRCA (N = 1043(R = 0.103690910291636, P = 0.000797159290285103), and a significant negative association in 4 tumors." (PMID 38031089, 2023). "Our in vitro and in vivo findings suggest that SIX1 may repress tumor progression." (PMID 37468459, 2023).
tumor (continued). "Similarly, we found that overexpression of SIX1 could promote the proliferation and tumor growth of NSCLC, while knockdown of SIX1 exhibited the opposite effect." (PMID 35069900, 2022). "Moreover, SKCM metastatic tissues showed higher SIX1 mRNA level than SKCM primary tumor tissues." (PMID 35069900, 2022). "Additionally, overexpression of different EMT-TFs, including Slug, Twist, Six1 and Snai1, promoted stemness and tumor initiation capacity, whilst EMT-TF knockout had a tumor-preventative effect (e.g., Slug-knockout mice were resistant to MMTV-Myc-induced tumor initiation)." (PMID 34072345, 2021). "Given that Six1 deletion suppressed tumor growth in a manner dependent on CD8+ T cells, which belong to the adaptive immune system, we hypothesized that Six1−/− tumor cells, by triggering antitumor immunity, may protect the host from challenge with the corresponding WT tumor cells." (PMID 34782761, 2021). "Thus, our first objective was to determine if suppression of senescence could play a role in the tumor-promoting action of SIX1." (PMID 30723235, 2019). "Anyway, functional activation of SIX1 may promote tumor progression." (PMID 27821176, 2016). "Our results suggested that Six1 might play an essential role in tumor proliferation." (PMID 23527134, 2013). "However, treatment of MCF7-Ctrl injected mice with AZD6244 also significantly inhibited tumor initiation, suggesting that the MEK/ERK pathway is critical in tumor initiation in multiple contexts and that increased Six1 amplifies a pathway that is already required for tumor initiation." (PMID 22765220, 2012). "In support of this hypothesis, we have shown that aberrant expression of Six1 in adult mammary cells reinstates a pro-proliferative and pro-survival program that likely contributes to Six1-dependent transformation and tumor formation in xenograft and transgenic mouse models." (PMID 22765220, 2012). "In pancreatic cancer, SIX1 directly binds to the promoter region of LDHA, triggering glycolysis in tumor cells to promote lactate accumulation, leading to NK cell dysfunction." (PMID 40696413, 2025). "The results revealed that tumor cells exhibited significantly elevated expression levels of WT1, SIX1, SIX2, and CITED1, supporting the accurate annotation of tumor cells." (PMID 40534868, 2025). "Here, we show that sine oculis homeobox 1 (SIX1) phosphorylation integrates growth factors (e.g. TGFβ, EGF) to control aerobic glycolysis and determines its tumor-promoting activity." (PMID 39617783, 2024). "Similarly, our results reveal that as SIX1 expression increases, there is a decrease in overall immune cell infiltration and an increase in M2 macrophages and Treg cells, potentially leading to the suppression of other immune cells and favoring tumor cell growth." (PMID 38031089, 2023). "SNS-032 was able to induce the degradation of SIX1 through the inactivation of the EGFR-AKT-USP1 axis, and SNS-032 in combination with sorafenib was found to inhibit tumor growth in a mouse model of HCC." (PMID 36750914, 2023). "SIX1 was found to synergize with the transcriptional cofactor EYA, which had tyrosine/threonine-phosphatase activity, to promote tumor initiation and progression." (PMID 36750914, 2023). "Based on orthotopic xeonograft tumours CCG99‐11 has previously been classified with blastemal like characteristics, including a slight SIX1 expression." (PMID 37186071, 2023). "Sine oculis homeobox homolog 1 (SIX1), a developmentally restricted transcriptional regulator, plays a critical role during tumor initiation and development." (PMID 35069900, 2022). "SIX1 directly regulates expression of glycolytic genes such as HK2 and PKM2, glucose uptake, and the level of lactate, a metabolite that can modulate tumor cell proliferation, apoptosis, and metastasis." (PMID 35193488, 2022).
tumor (continued). "The gene coding for the transcription factor SIX1, co-expressed with PAX3 and PAX7 in myogenic precursors, is highly expressed in human RMS tumours and has been reported to be a regulator of metastasis in mice models for RMS21." (PMID 36229514, 2022). "This tumor and EMT inducive role of Six1 seems to be through increased levels of ZEB1, SNAIL1, and TWIST1." (PMID 37305018, 2022). "SIX1 activates the transcription of potent oncogenes and stem cell regulators, such as c-MYC and ezrin, that have a vital role in tumor invasion and signal transduction in many cancers." (PMID 34771571, 2021). "We also performed IHC staining of other top-ranked TFs including SIX1, RUNX1, and SOX4 and again found higher expression level of these TFs in tumor tissues." (PMID 34001209, 2021). "The results of this study show that miR-7160, a potential tumor suppressor, can inhibit NSCLC cell growth by silencing its target gene SIX1." (PMID 33686961, 2021). "SIX1 induces EMT and is found to be a crucial mediator to the switch of the TGF-β signalling pathway from a tumour suppression to tumour promotion." (PMID 34238352, 2021). "The Six1/TGF-β pathway appears to switch cells toward a pro-EMT fate, an important step toward tumor metastasis." (PMID 34490256, 2021). "Our studies revealed a tumor suppressive role of Suv39h1 in MLL-r AML that is partially mediated by inactivation of Hoxb13 and Six1, as well as reversion of Hoxa9/Meis1 downstream transcriptomes." (PMID 33037410, 2020). "For example, TGF-β increases the expression of VEGF-C by coordinating with sine oculis homeobox homolog 1 (SIX1) in tumor cells, promoting tumor lymph angiogenesis and lymph node metastasis." (PMID 31195692, 2019). "To identify the expression pattern of SIX1 and EYA1 in human thyroid tissue as well as tumor, we performed IHC analysis by using two tissue microarrays (TH8010 and TH802a)." (PMID 31921695, 2019). "SIX1 and EYA can integrate with other signal pathways to modulate the apoptosis, cell proliferation and tumor growth." (PMID 31921695, 2019). "We show that Six1 is overexpressed in human PDAC and that its inhibition results in a decreased tumour progression in vitro and in vivo." (PMID 28388884, 2017). "Overall, our data suggest that in a fraction of relapsing WT patients SIX1 and DROSHA mutations might be (whether spatially or temporally) heterogeneous events within the primary tumor, which are positively selected in the process of tumor progression to recurrence." (PMID 26802027, 2016). "Our data add to this scenario the possibility that alterations of the SIX1 and DROSHA genes occur also at later stage, driving tumor evolution toward chemotherapy resistance and recurrence." (PMID 26802027, 2016). "In contrast, SIX1 promotes EMT in a TGF-β signaling-dependent manner, and is a critical enhancer in the switch of TGF-β/SMAD from tumor suppressors to oncogenic proteins." (PMID 27203207, 2016). "During our analysis the most prominent differences connected with the location of the tumor were noted for the IRX2, PAX3, CXCL14, LHX2, SIX6, CNTN1 and SIX1 genes." (PMID 26497896, 2015). "While we observe a trend (P=0.06) towards a positive correlation between Six1 and miR-27a expression in human patient tumour data sets, the inverse correlation between Six1 and RPL26 appears to be much stronger in patient tumours." (PMID 26687066, 2015). "Within the paper, we use numerous means to conclusively demonstrate that Six1 induces a TIC phenotype through both TGF-β and ERK signaling, including examination of surface markers, tumorsphere assays, and in vivo tumor initiating assays." (PMID 22765220, 2012). "In conclusion, our data indicated that Six1 protein was specifically and frequently expressed in HCC tumour tissues." (PMID 17008870, 2006).
tumor (continued). "Notably, several homeodomain transcription factors were overexpressed in SFTs (ALX4, SHOX2, SIX1) and entire HOX clusters (HOXA, HOXC) were upregulated, as further confirmed by RNAPII profiling of a primary tumor tissue." (PMID 40875449, 2025). "SIX1 has largely been studied in the context of FN-RMS where it was found that KD of SIX1 results in large-scale, genome-wide changes in transcription and leads to marked tumor cell differentiation." (PMID 39902277, 2024). "In addition, among the enriched TFs in NN-HF, we further identified NFκB-P65, FOXA3, FOXD3, SIX1, CDX2, and MEF2C which have been found to impact tumor progression." (PMID 38720110, 2024). "In addition, we found that the insulin/lncRNA DGUOK‐AS1/microRNA‐145‐5p (miR‐145‐5p) axis controls SIX1 expression, DNL, and tumor growth and metastasis." (PMID 39258807, 2024). "Functionally, we demonstrated that the silencing of SIX1, SIRT2 and CDKN2A expression could accelerate the migratory and invasive capacities of tumor cells, whereas the downregulation of PGR dramatically inhibited cancer cells migration and invasion." (PMID 37723477, 2023). "Likewise, sine oculis homeobox homolog 1 (SIX1) and protein tyrosine phosphatase receptor type M (PTPRM) expressed in tumor cells both promote tumor lymphangiogenesis by inducing increased expression of VEGF-C." (PMID 37234990, 2023). "Moreover, miR-30b can inhibit the PI3K/AKT signaling pathway through the regulation of EGFR, AKT, Derlin-1, GNA13, SIX1, and other target genes, thus inhibiting the EMT process of tumor cells and promoting apoptosis." (PMID 35291564, 2022). "The results showed an increasing trend of TUG1 levels, a decreasing trend of miR-524-5p levels, and an increasing trend of SIX1 levels in adjacent non-tumor, non-metastatic HCC, and metastatic HCC tissues." (PMID 35193488, 2022). "To investigate the relationship among TUG1, miR-524, and SIX1, we investigated the levels of TUG1, miR-524, and SIX1 in adjacent non-tumor, non-metastatic HCC, and metastatic HCC tissues." (PMID 35193488, 2022). "On the other hand, due to the technical barrier, this study evaluated the in vivo anti-CRPC effects of the SIX1 degradation inducer by the establishment of subcutaneous tumor xenograft, but not orthotopic transplantation in the prostate." (PMID 35414775, 2022). "To understand how Six1 deletion in cancer cells triggers an adaptive immune response to limit tumor growth, we performed transcriptomic RNA-sequencing (RNA-seq) analysis of WT and Six1−/− MCA205 tumor tissue samples (GSE183580)." (PMID 34782761, 2021). "Previous studies demonstrated that miR-889 could regulate the tumor cellular behaviors by targeting serval target genes, such as KLF9, SIX1, DAB2IP, TAB1, FGFR2, TWEAK." (PMID 34116691, 2021). "Increased levels of SIX1 gene or protein expression was often found to be strongly correlated with poor prognosis regardless of tumor type." (PMID 34490256, 2021). "In addition, these findings indicated that miR-140-5p functions as a tumor suppressor and plays a critical role in CML cell apoptosis and metabolism by targeting SIX1." (PMID 30962263, 2019). "In addition to its physiological role in organogenesis, it has also been shown that SIX1, and other SIX proteins, act as oncogenes in a variety of tumor types, including lung, breast, brain and colorectal tumors." (PMID 30723235, 2019). "To establish if our results could reflect a general link between SIX1 and SOX2 in cancer, we decided to investigate this connection in a different tumor type." (PMID 30723235, 2019). "Two tumours with MLLT1 mutations also had CTNNB1 mutations; no MLLT1-mutant tumours had accompanying WT1, WTX, DROSHA, DGCR8, SIX1, or SIX2 mutations." (PMID 26635203, 2015).
tumor (continued). "Cripto-1 has been shown to be involved in tumor epithelial cell plasticity and may be an important EMT regulator together with downstream genes such as Snail, Slug, Twist, and Six1." (PMID 26059540, 2015). "Overexpression of Six1 mRNA was found in about 85% (61 of 72) of tumour tissues compared with nontumour tissues." (PMID 17008870, 2006). "About 85 and 60% of HCC tumour tissues were found to overexpress Six1 mRNA and protein, respectively, compared with nontumour liver tissues." (PMID 17008870, 2006). "Western blot analysis showed that near 60% (61 of 103) of tumour tissues expressed Six1 protein while no nontumour tissue expressed Six1 protein." (PMID 17008870, 2006). "We also do not know whether SIX1 phosphorylation is critical for growth factor modulation of tumor growth and metastasis." (PMID 39617783, 2024). "Yet, the transcriptional regulatory consequences of SIX1/2-Q177R that might promote tumor progression and recurrence have not been investigated extensively." (PMID 37815464, 2023). "The homeoprotein Six1, a member of the Six family of homeodomain transcription factors, increases the expression of CCL2, CCL5, and vascular endothelial growth factor (VEGF), attracts macrophage infiltration into the tumor, and further leads to CRC tumor growth, progression, and metastasis." (PMID 35935996, 2022). "We found that the levels of SIX1 and EYA1 expression were significantly associated with age, lymph node metastasis (two sample missed this information, tissue ID: Etg030430 and Etg030007) and clinical stage, but not tumor size." (PMID 31921695, 2019). "Interestingly, of the EMT-TFs, Six1, the central mediator downstream of Twist1 and Snail1, significantly correlated with percent of PDX-bearing mice in which circulating tumour cells were found, suggesting a potential key role for this EMT-TF in metastatic dissemination." (PMID 28604738, 2017). "Possible explanation is that no-tumor cell contamination in no-microdesected tumor tissue may attenuate the real expression level of SIX1 in cancer." (PMID 27821176, 2016). "While the involvement of SIX1 in cytokine secretion and immune regulation is yet to be established, the current evidence suggests that an imbalance in the RDGN would create a favorable microenvironment to enhance the survival of cancer cells and their escape from the primary tumor." (PMID 27203207, 2016). "In addition, gaining an understanding of how Six1 regulates miR-27a and RPL26 may be important in the future for identifying novel ways to resensitize tumours to Nutlin-3 therapies." (PMID 26687066, 2015). "Sufficient DNA was available on 16/19 MLLT1-mutant tumours to perform mutation analysis for WT1, CTNNB1, WTX, DROSHA, DGCR8, and SIX1/2 and this revealed five CTNNB1 mutations, one WTX mutation, and no WT1 DROSHA, DGCR8, or SIX1/2 mutations." (PMID 26635203, 2015). "Thus, it is possible that decreases in primary tumor burden influence the extent of metastasis both with MEK inhibition and Six1 inhibition, although Six1 inhibition has recently been shown to influence metastasis independent of primary tumor size." (PMID 22765220, 2012). "In fact, high expression of Six1 does not predict poor prognosis in other tumor subtypes." (PMID 22765220, 2012). "In addition, expression of Six1 protein in liver is probably to be tumour-specific indicated by the evidence that no Six1 protein was expressed in both normal liver tissues and HCC nontumour liver tissues." (PMID 17008870, 2006). "Interestingly, tumors derived from WT cells grew slightly larger than those derived from Six1−/− cells in nude mice at the late stage, suggesting that SIX1 may also have some potential intrinsic effects on tumor growth independent of the immune response." (PMID 34782761, 2021).